CCL2 (C-C motif chemokine ligand 2)
Diseases named in the same sentence as CCL2 in open-access papers (continued):
Sharing a sentence is not in itself a finding about the gene and the disease.
Kawasaki disease (2 papers, 2023 to 2025). A rare inflammatory disease characterized by an acute febrile, systemic, self-limiting, medium-vessel vasculitis primarily affecting children. "T cells further recruit immune cells to the vessel wall by secreting cytokines such as IL-1β, TNF-α and chemokines such as CCL2.In animal models, CD8+ T cells are essential for the development of vascular inflammation in Kawasaki disease." (PMID 40746545, 2025).
laryngeal carcinoma (2 papers, 2009 to 2020). Carcinoma that arises from the laryngeal epithelium. "Examination of serum CCL2 and TNF-α in 297 patients with pretreatment laryngeal cancer showed that CCL2 and TNF-α levels were independent predictors of overall survival and distant metastasis-free survival." (PMID 33297571, 2020).
Legionella infection (2 papers, 2024). "the GSEA results showed that CXCL8, IL1B and CCL2 affect Graft-versus-host disease, Legionellosis, Primary immunodeficiency, Primary bile acid biosynthesis, Protein export and Non-homologous end-joining signaling pathways." (PMID 38167125, 2024).
liposarcoma (2 papers, 2019 to 2021). A usually painless malignant tumor that arises from adipose tissue. "Anti-CSF1R and anti-CCL2 blocking antibodies in combination with chemotherapy are in phase I/II clinical trials in pancreatic, breast, and liposarcoma cancers." (PMID 31878276, 2019).
lung neoplasm (2 papers, 2024). A benign or malignant, primary or metastatic neoplasm involving the lungs. "In another way, HDM promoted the expression of monocyte chemoattractant protein-1 (CCL2), which attracted more macrophages into the lung tumor microenvironment." (PMID 38542056, 2024).
malignant mesothelioma (2 papers, 2013 to 2023). A malignant neoplasm of the pleura or peritoneum, arising from mesothelial cells. "In contrast, in the malignant mesothelioma cell line panel, CCL2 expression was downregulated compared to the marked increase in CXCR2-dependent chemokines, IL-1α, and VEGF-A underscoring the critical role played by cell type in the context of arginine deprivation therapy." (PMID 37010783, 2023).
myopic macular degeneration (2 papers, 2024 to 2025). "Levels of tear IL−6 and CCL2/MCP−1 have been shown to correlate with axial length and may serve as predictive biomarkers for myopic macular degeneration." (PMID 40909333, 2025).
nematode infection (2 papers, 2015 to 2018). "Finally, elevated resistin was associated with higher concentration of IL-6, CCL2 and TNFα and inflammatory factors, suggesting that the resistin/proinflammatory cytokine immune axis we identified in mice is also present in human nematode infections." (PMID 25568944, 2015). "This high CCL2 fluorescence signal on the surface of the intestinal epithelium of infected mice is a consequence of the Th2 induction after a nematode infection." (PMID 29773890, 2018).
nephrotic syndrome (2 papers, 2016 to 2024). A collection of symptoms that include severe edema, proteinuria, and hypoalbuminemia; it is indicative of renal dysfunction. "Urinary excretion of interleukin-18 (IL-18)/CXCL8, MCP-1/CCL2, and RANTES/CCL5 was not different in an analysis of patients with steroid-resistant or steroid-sensitive nephrotic syndrome." (PMID 26989679, 2016).
nosocomial infection (2 papers, 2022 to 2024). An infection acquired in a hospital or other healthcare setting. "Third, CCL2 blockade is known to prime cell response to infection and to reduce cell-killing properties which are underdeveloped in preterm infants and are thereby at increased risk for nosocomial infections due to their immature immune system." (PMID 38961074, 2024). "For example, it is well-established that IL-6, IL-8, IL-10, and MCP-1 (CCL2) are elevated early after injury and are correlated with adverse outcomes including nosocomial infection, multiple organ dysfunction syndrome, and mortality." (PMID 36532045, 2022).
ocular infection (2 papers, 2018 to 2021). "Both CCL2 and CCL3 were upregulated in the context of TLR4-mediated inflammation after B. cereus ocular infection, and their blockade might reduce neutrophil infiltration into the vitreous and decrease damage to the retina." (PMID 29661181, 2018).
ocular toxoplasmosis (2 papers, 2023 to 2025). Ocular toxoplasmosis is an infection in the eye caused by the parasite, Toxoplasm a gondii. "In another study, patients with ocular toxoplasmosis displayed high levels of IFN-induced chemokines CXCL9 and CXCL10 and circulating chemokines CCL25, CCL11, CXCL12, CXCL13, and CCL2." (PMID 36755348, 2023).
otitis media (2 papers, 2010 to 2024). Inflammation of the anatomical structures of the middle ear, which is most often caused by an infectious process. "Similarly, spiral ligament fibrocytes may secrete CCL2 which has been found to be responsible for inner ear inflammation and monocyte attraction in experimental otitis media." (PMID 38817543, 2024).
ovarian adenocarcinoma (2 papers, 1999 to 2005). An adenocarcinoma that arises from the ovary. "We first detected CCL2 as a gene whose expression is downregulated in ovarian adenocarcinoma cell lines relative to OSE cells by cDNA array." (PMID 15900302, 2005). "However, we did not detect any mutations in the CCL2 coding sequence in 94 primary ovarian adenocarcinomas." (PMID 15900302, 2005). "No CCL2 expression was detected in the remaining seven ovarian adenocarcinoma cell lines, even after 36 rounds of PCR amplification." (PMID 15900302, 2005). "There were no aberrant bands detected in the PCR of any exon of CCL2 in the panel of 94 primary ovarian adenocarcinomas tested." (PMID 15900302, 2005).
peripheral vascular disease (2 papers, 2013 to 2025). Any disorder affecting blood flow through the veins or arteries outside of the heart. "Furthermore, expression and secretion of CCL-2, CCL-5 and CX3CL-1 by human coronary artery endothelial cells as well as monocytes was inhibited by preincubation with rHDL, and rHDL (CSL111; 80 mg/kg) infused in patients with peripheral vascular disease decreased CD11b on neutrophils." (PMID 23967171, 2013).
pertussis (2 papers, 2013). A contagious bacterial respiratory infection caused by Bordetella pertussis. "Transgenic overexpression of CCL2 in astrocytes only leads to neurological impairment after systemic injection of pertussis." (PMID 23232206, 2013). "Other authors have demonstrated that a transgenic mouse that expressed CCL2 under the GFAP promoter developed pertussis-induced reversible inflammatory encephalopathy and that CCL2 directed a Th1-biased inflammatory reaction, as shown by high levels of TNF-α, INFγ and IL-2 in the CNS." (PMID 23866683, 2013).
pituitary adenomas (2 papers, 2023 to 2024). "In summary, IL‐6, CCL2, EGF/EGFR, VEGF/VEGFR, and other cytokines are expressed in pituitary adenomas and are generally related to their aggressiveness, occurrence, and development." (PMID 38738958, 2024). "A high expression of CCL2, CXCL10, CX3CL1, with a low number of infiltrating FOXP3 T-cells and a high number of infiltrating CD4+ T-cells was detected in highly vascularized pituitary adenomas/PitNets." (PMID 36658300, 2023). "Interestingly the secretion of CCL2 was further increased in GH3 cells that derived from highly vascularized and highly proliferative pituitary adenomas/PitNets." (PMID 36658300, 2023).
pleural mesothelioma (2 papers, 2022 to 2025). A neoplasm that arises from the mesothelial cells of the pleura. "Recent study reports that EZH2 inhibitor EPZ-6438 triggers malignant pleural mesothelioma cells to express high level of different monocytes chemoattractants, including CCL2 and CSF1, which lead to increased monocytes recruitment in tumor spheroids as well as M2 TAMs differentiation." (PMID 36038549, 2022).
polycythemia vera (2 papers, 2015 to 2021). "We recently demonstrated that patients with post-polycythemia vera/essential thrombocythemia MF are enriched in the polymorphic allele variant of the rs1024611 SNP of CCL2, and its presence correlates with adverse clinical features." (PMID 34067466, 2021).
prostate adenocarcinoma (2 papers, 2005 to 2020). "After analyzing human prostate adenocarcinomas in The Cancer Genome Atlas (TCGA) Program, the IL1RN was indeed tightly correlated with both CCL2 and CXCL1." (PMID 33322099, 2020).
Prostatic intraepithelial neoplasia (2 papers, 2023). "Macrophage-secreted molecules have also been associated with PCa development, such as C5a, CXCL1, and CCL2, by increasing prostatic intraepithelial neoplasia (PIN) cell proliferation." (PMID 37090711, 2023). "Prostatic intraepithelial neoplasia (PIN) is characterized by inflammation and is associated with an increase in CXCR2 expression compared to healthy tissue as well as an increase in CCL2/MCP-1 levels, which causes the recruitment of macrophages." (PMID 37108425, 2023).
Pruritus (2 papers, 2022 to 2023). Pruritus is an itch or a sensation that makes a person want to scratch. "Among the studied chemokines (C-C Motif Chemokine Ligand (CCL) 2/MCP-1, CCL3/MIP-1α, CCL4/MIP-1β, CCL5/RANTES, CXCL8/IL-8, CCL17/TARC, CCL18/PARC, CCL22/MDC), only CCL17/TARC showed a positive correlation with pruritus intensity." (PMID 37834183, 2023). "The aim of the study was to analyse serum concentrations of CCL2/MCP-1, CCL3/MIP-1α, CCL4/MIP-1β, CCL5/RANTES, CCL17/TARC, CCL18/PARC, CCL22/MDC and CXCL8/IL-8, and their correlation with PsO severity and pruritus intensity." (PMID 36362116, 2022).
radiation pneumonitis (2 papers, 2022 to 2023). Inflammation of the lung due to harmful effects of ionizing or non-ionizing radiation. "Moreover, translational investigations using patient samples collected before and after thoracic radiotherapy provided additional evidence supporting the association between cGAS-STING signaling activity, CCL2 upregulation, and the development of radiation pneumonitis." (PMID 37667317, 2023).
retinal dystrophies (2 papers, 2012 to 2013). "Nevertheless, modulation of Ccl2 expression using appropriately targeted RNAi may provide a powerful means to control excessive microglial recruitment and activation in retinal dystrophies such as AMD." (PMID 22992301, 2012).
retinal vein occlusion (2 papers, 2018 to 2022). An occlusion of the retinal vein. "Treatment with CCL2 could promote macrophage-like cells recruited on the retina surface, a characteristic of vision-threatening retinal vascular diseases like DR and retinal vein occlusion." (PMID 36686430, 2022).
ROSAH syndrome (2 papers, 2022 to 2023). "Consistent with the observations in patients with ROSAH syndrome, knock-in mice with the Alpk1 T237M mutation had elevated serum levels of CXCL1, CXCL10 and CCL2." (PMID 35868845, 2022).
Sciatica (2 papers, 2024 to 2025). Pain in the lower back and hip radiating in the distribution of the sciatic nerve. "For instance, several key chemokines including CCL2, CCL11, CXCL5, CXCL6, and IL-16 were positively associated with sciatica." (PMID 39015317, 2024). "The CCL2 measurement (p = 0.046, OR = 1.00115, 95% CI = 1.00002–1.00227), monocyte chemotactic protein-4 measurement (p = 0.027, OR = 1.00112, 95% CI = 1.00013–1.00211), protein S100-A12 measurement (p = 0.009, OR = 1.00113, 95% CI =1.00028–1.00198) are positively correlated with sciatica." (PMID 39015317, 2024). "We speculate that in the early-stages of sciatica, the accumulation of neutrophils and other immune cells released inflammatory mediators like IL-6, TNF-α, and CCL-2 at the injury site." (PMID 41424922, 2025).
skin reaction (2 papers, 2006 to 2022). "Luteolin and quercetin may be the core active ingredients of QYSLS in the treatment of EGFRI-related adverse skin reactions, and their therapeutic effects are potentially mediated through PTGS2, CCL2, and MMP9 in the IL-17 and TNF signaling pathway." (PMID 35372072, 2022).
soft tissue sarcoma (2 papers, 2020 to 2021). A malignant neoplasm arising from muscle tissue, adipose tissue, blood vessels, fibrous tissue, or other supportive tissues excluding the bones. "Furthermore, in soft tissue sarcoma patients, high CCL2 mRNA expression is associated with a good prognosis, and higher CCL2 expression was significantly associated with better OS in non-small-cell lung cancer (NSCLC) patients." (PMID 32429318, 2020). "Additionally, the coexpression of CCL2 and CX3CL1 was strongly associated with prognosis of patients with soft tissue sarcoma, particularly female patients." (PMID 34616731, 2021).
ST Elevation Myocardial Infarction (2 papers, 2012 to 2022). A myocardial infarction that produces elevation in the ST segments of the ECG. "A study, examining the expressions of CCL2 and CCR2 in the plasma, found that in 80 STEMI (ST-Elevation Myocardial Infarction) patients with platelet high response, patients had higher expressions of CCL2 or CCR2 than those patients with a platelet normal response." (PMID 35749425, 2022).
Streptococcus pneumonia (2 papers, 2017 to 2020). "As recently reported, NOD2 recognizes lysozyme-digested PGN processed by professional phagocytes and releases chemokine MCP-1/CCL2 to recruit additional monocytes/macrophages to restrict/clear Streptococcus pneumonia colonization in mice." (PMID 28165033, 2017).
Tay-Sachs disease (2 papers, 2020 to 2025). GM2 gangliosidosis, variant B or Tay-Sachs disease is marked by accumulation of G2 gangliosides due to hexosaminidase A deficiency. "GM2 accumulation triggers chronic neuroinflammation due to neurodegeneration-based astrogliosis and macrophage activity with the increased expression level of Ccl2 in the cortex of a recently generated Tay-Sachs disease mouse model Hexa-/-Neu3-/-." (PMID 40019557, 2025).
toxoplasmosis (2 papers, 2014 to 2024). A parasitic disease contracted by the ingestion or fetal transmission of toxoplasma gondii. "Generally, CCL2 shows a local and systemic activity associated with T. gondii elimination in experimental models and humans, and its elevated expression and production correspond with the chronic state of toxoplasmosis of the central nervous system." (PMID 38835777, 2024). "CCR2−/− mice or CCL2−/− mice failed to recruit Gr1+ inflammatory monocytes, which are required for mucosal resistance to T. gondii, or to control systemic toxoplasmosis by intraperitoneal infection." (PMID 24661782, 2014).
Trichiasis (2 papers, 2012 to 2019). Inversion and rubbing of the eyelashes against the globe of the eye. "Previously, we have identified CCL2 as a risk factor for trichiasis, and therefore analyzed the effect of 405 nm irradiation on C. trachomatis induced CCL2 production." (PMID 22894815, 2012). "Furthermore, we analyzed the effect of this photo treatment on the ensuing secretion of IL-6 and CCL2, two pro-inflammatory cytokines that have previously been identified as immunopathologic components associated with trichiasis in vivo." (PMID 22894815, 2012). "The upregulation of pro-inflammatory mediators and cell markers (CCL2, CCL3, CXCL5,IL1B, IL6, CHUK, FUT4 andPTPRC) is indicative of higher levels of inflammation and leukocyte infiltration in the conjunctival tissue of patients who developed ECA following trichiasis surgery." (PMID 37426632, 2019).
trichomonas infection (2 papers, 2020 to 2025). "The adhesion of Tv to vaginal epithelial cells is pivotal in the pathogenesis of trichomoniasis, facilitating the production of pro-inflammatory cytokines such as IL-8, CCL2, and IL-6." (PMID 40813994, 2025).
uremia (2 papers, 2021 to 2025). A clinical syndrome associated with the retention of renal waste products or uremic toxins in the blood. "Macrophages exposed to uremia also demonstrate increased expression of CCL2, an important macrophage-attractant chemokine as well as surface markers associated with a metabolically activated macrophage phenotype." (PMID 33536542, 2021). "The source of increased ATMS in uremia needs to be determined but higher numbers of circulating peripheral monocytes in uremia as well as elevated CCL2 and IL-6 in the cell models suggest a preferential role of monocyte recruitment to adipose tissue." (PMID 33536542, 2021). "Adipose cells exposed to uremia-primed macrophages showed increased IL-6 and CCL2 expression in the human and murine models." (PMID 33536542, 2021). "Both cell lines exposed to uremia have also a significant increase in the expression of IL-6, TNFα, and CCL2 without changes in expression of anti-inflammatory cytokines." (PMID 33536542, 2021).
vascular dementia (2 papers, 2018 to 2024). A degenerative vascular disorder affecting the brain. "Scholars have found that the levels of CCL2 in the serum of patients over 60 years old with vascular dementia are significantly elevated." (PMID 39206161, 2024).
adenosquamous carcinoma (1 paper, 2016). A carcinoma composed of malignant glandular cells and malignant squamous cells. "The exact mechanism underlying the link of rs3760396 of CCL2 with adenosquamous carcinoma would need further investigation." (PMID 27145753, 2016). "Interestingly, the association of CCL2 with adenocarcinoma or adenosquamous carcinoma in other tissue types has been reported." (PMID 27145753, 2016). "Our study further indicated the potential link of CCL2 rs3760396 with the adenocarcinoma cell components shared between adenosquamous carcinoma and adenocarcinoma." (PMID 27145753, 2016).
adenosquamous lung carcinoma (1 paper, 2016). An aggressive carcinoma with a poor prognosis characterized by a presence of both malignant squamous cells and glandular cells. "Our current study found that the minor allele G of genetic polymorphism in CCL2 gene, rs3760396, was significantly associated with increased risk of adenosquamous lung carcinoma, after controlling for age, gender, and smoking status." (PMID 27145753, 2016).
adenovirus infection (1 paper, 2010). "CXCL1 and CCL2 have been shown to be expressed in adenovirus infection and are paradigm chemokines responsible for neutrophil and monocyte chemotaxis, respectively." (PMID 20419141, 2010).
African trypanosomiasis (1 paper, 2018). "The expression of this chemokine in the brain during African trypanosomiasis remains to be explored, but CCL2 is part of the panel of inflammatory mediators increased in the CSF of T. b." (PMID 29535612, 2018).
alcohol addiction (1 paper, 2013). "More recently, the expression of the chemokine (C-C motif) ligand 2 (CCL2) was shown to be elevated in the CNS of the brains of human chronic alcoholics with a mean age of 61 to 64 years, which may suggest that CCL2 plays an important role in alcohol addiction." (PMID 23701841, 2013).
allergic conjunctivitis (1 paper, 2019). "In a mouse model of ragweed-pollen-induced allergic conjunctivitis, treatment with an anti-CCL2 Ab inhibited eosinophilic recruitment." (PMID 31921102, 2019). "The effect of CCL2 on mast cells in allergic reactions has been shown in a mouse model of ragweed-pollen-induced allergic conjunctivitis, where blocking of CCL2 or its receptor CCR2 by antibodies suppressed clinical signs of hyperreactivity and mast cell degranulation in the animals." (PMID 31921102, 2019).
amyloidoma (1 paper, 2024). Nodular localized form of amyloidosis with predominantly thoracic localization (pulmonary amyloidosis), considered as secondary protein structure disease in which insoluble protein fibrils accumulate extracellularly. "ALκ(TAL) amyloidomas had significantly more expression of monocyte chemoattractant protein-1 (MCP1; CCL2), and more expression of tumor necrosis factor-alpha trending towards significance (p=0.0627)." (PMID 39600710, 2024).
aortitis (1 paper, 2023). Inflammation of the aorta. "It was found that resident macrophages produce CCL2, which induces the recruitment of inflammatory monocytes (iMos) into the aortic root, the first step required to trigger aortitis." (PMID 36830768, 2023).